OGG1 (8-oxoguanine DNA glycosylase)
Diseases named in the same sentence as OGG1 in open-access papers (continued):
Sharing a sentence is not in itself a finding about the gene and the disease.
asthma (7 papers, 2014 to 2025). "We have recently shown that OGG1-BER signaling induces gene expression associated with typical asthma symptoms." (PMID 27524866, 2016). "In this study, V-D-deficiency increased the OGG1 expression in severe asthma exacerbation compared to that in V-D-sufficiency." (PMID 25380286, 2014). "In addition, system biology approaches suggested that the repair product of oxidatively damaged DNA by OGG1 induces gene expression associated with airway inflammation, asthma, and EIA related symptoms." (PMID 27524866, 2016). "Recently, it has been proposed that OGG1-driven DNA base excision repair has a role in asthma pathogenesis." (PMID 27524866, 2016). "In this study, the patients with severe asthma exacerbation showed increased ROS, DNA damage and OGG1 in the peripheral blood mononuclear cells." (PMID 25380286, 2014). "V-D-deficiency intensified ROS release and DNA damage and increased TNF-α, OGG1 and NFκB expression and NFκB phosphorylation in severe asthma exacerbation." (PMID 25380286, 2014). "Similarly, in an asthma model, the cell infiltration in the airway, perivascular and alveoli and the secretion of Th1, Th2 and Th17 cytokines of Ogg1-/-mice were slighter." (PMID 35624797, 2022). "Whole-genome expression analysis also suggests that the OGG1-BER-induced gene expression may play a role in asthma and EIA Pathophysiology." (PMID 35624797, 2022). "Animal models in which OGG1 has been shown to promote inflammation include contact hypersensitivity (skin inflammation;), endotoxin shock (generalized, “whole body” inflammation), asthma, Pseudomonas infection, hypoxia-reoxygenation-induced neuroinflammation and TNF-induced lung inflammation." (PMID 36289805, 2022). "Therefore, OGG1 could be a potential target for aging-related diseases and chronic inflammation such as asthma, COPD and so on." (PMID 35624797, 2022). "This hypothesis is supported by previous studies from other research groups and from our own research group, showing the involvement of OGG1-BER in gene expression related to airway inflammation and other asthma features." (PMID 27524866, 2016).
cervical carcinoma (7 papers, 2010 to 2025). A carcinoma arising from either the exocervical squamous epithelium or the endocervical glandular epithelium. "In gynecologic oncology, polymorphisms in the OGG1 gene have been linked to the risk and progression of cancers such as ovarian and cervical cancer." (PMID 40813502, 2025). "ROS-inducing agents promote parthanatos in cervical cancer cells by inducing DNA strand breaks via OGG1-mediated excision of 8-oxoG." (PMID 40813502, 2025). "In this experiment, we found that TDG and LIG1 were expressed at high levels in cervical cancer, and OGG1 expression was low in cervical cancer (P < 0.05)." (PMID 35379200, 2022). "The expression level of OGG1 was lower in the CIN group than the normal group (P < 0.05) but higher than in cervical cancer group (P < 0.05)." (PMID 35379200, 2022). "Moreover, ROS inducers trigger parthanatos in cervical cancer cells through excessive excision of 8-oxoG mediated by OGG1, leading to extensive DNA strand breaks." (PMID 40813502, 2025). "The same was found when the DNA repair candidate genes from cervical carcinoma (MSH5, OGG1) and lung squamous cell carcinoma (CHEK1) were analyzed." (PMID 27683114, 2016). "However, expression levels of TDG, LIG1 and OGG1 have not been examined in cervical cancer tissues." (PMID 35379200, 2022). "This study showed that the DNA repair pathway involved in OGG1 was closely related to oesophageal cancer, but its expression in CIN and cervical cancer has not yet been reported." (PMID 35379200, 2022). "In cervical carcinoma, VTCN1 exhibited a negative correlation with OGG1 and RAD51B methylation that was statistically significant after Bonferroni correction (p=0.009, p=0.015, respectively)." (PMID 27683114, 2016).
kidney tumor (7 papers, 2008 to 2025). "The purpose of this study is to determine the effect of tuberin-deficiency on OGG1 protein and mRNA levels as well as on 8-oxodG levels in kidney tumors from patients with TSC." (PMID 19265534, 2009). "The deficiency of tuberin was associated with a significant decrease in NF-YA and loss of OGG1 in kidney tumors of Eker rat." (PMID 20040097, 2009). "Deficiency in tuberin results in decreased OGG1 and NF-YA protein expression and increased 8-oxodG in kidney tumor from TSC patients." (PMID 20040097, 2009). "OGG1 is a common mutation site in renal tumors such as renal clear cell carcinoma." (PMID 36620083, 2022). "In addition, tuberin haploinsufficiency is associated with the loss of OGG1 and accumulation of 8-oxodG in rat kidney tumor." (PMID 20040097, 2009). "This study is the first report that the loss of tuberin is associated with loss of OGG1 suggesting that both proteins may play a major role in development of kidney tumor in Eker rat." (PMID 18218111, 2008). "However our new published data show that loss of OGG1 expression in kidney tumor tissue from Eker rat resulted in the accumulation of significant amounts of 8-oxodG (unrepaired DNA lesions), suggesting that loss of tuberin is biologically relevant in affecting OGG1." (PMID 19265534, 2009). "This study is the first report to demonstrate that deficiency of tuberin in patients with tuberous sclerosis is associated with significant decrease of OGG1 and accumulation of 8-oxodG in angiomyolipomas suggesting that both proteins may play a major role in development of this kidney tumor." (PMID 19265534, 2009). "Indeed, the loss of OGG1 expression in kidney tumor tissue from Eker rat resulted in the accumulation of significant amounts of 8-oxodG (unrepaired DNA lesions), suggesting that loss of tuberin was biologically significant in affecting OGG1." (PMID 18218111, 2008). "It was ascertained that OGG1 is localized to chromosome 3p25, a region that exhibits frequent loss of heterozygosity (LOH) in lung and kidney tumors." (PMID 40867876, 2025). "The OGG1 gene is located at 3p25 on chromosome 3, and a heterozygous deletion in the 3p25 region was found in 85% of 99 cases of renal tumor loci, including renal clear cell carcinoma." (PMID 36620083, 2022). "The human OGG1 gene (8-oxoguanine DNA glycosylase 1, gene ID 4968, also known as hMMH, MUTM and OGH1) is located at 3p26.2, a locus showing a frequent loss of heterozygosity (LOH) in many types of human cancers, including lung and kidney tumors." (PMID 23202958, 2012). "Decrease OGG1 results in the accumulation of 8-oxodG in kidney tumors, suggesting that tuberin plays a significant role in protecting the cells from oxidative DNA damage." (PMID 19265534, 2009). "The decrease in OGG1 mRNA in kidney tumor samples suggests that decreased transcription is one potential mechanism responsible for downregulation of OGG1 protein." (PMID 19265534, 2009). "The present study was conducted to investigate the effect of tuberin deficiency on phosphorylation of S6Kinase (downstream targets of mTOR) and on OGG1 expression and 8-oxodG levels in kidney tumors from TSC patients." (PMID 19265534, 2009). "In kidney tumors from Eker rats, the loss of the second TSC2 allele is associated with loss of OGG1 expression." (PMID 18218111, 2008). "OGG1 has been extensively studied in tumors, but less commonly in renal tumors." (PMID 36620083, 2022). "Rapamycin-mediated activation of AMPK and inhibition of mTOR upregulates OGG1, which may be a viable therapeutic target for renal tumors." (PMID 36620083, 2022). "In addition, tumor kidney of Eker rat show null tuberin and OGG1 expression indicating that tuberin is an upstream regulator of OGG1 protein and gene expression." (PMID 18218111, 2008).
non-small cell lung carcinoma (7 papers, 2011 to 2023). A group of at least three distinct histological types of lung cancer, including non-small cell squamous cell carcinoma, adenocarcinoma, and large cell carcinoma. "In a study of human non-small cell lung cancer, it was found that carriers who were positive for silencing of the DNA glycosylase OGG1 via methylation had a 2.25-fold higher risk of developing non-small cell lung cancer than carriers who did not exhibit OGG1 methylation." (PMID 29696001, 2018).
colon cancer (6 papers, 2007 to 2025). "Previously, inactivating mutations of DNA repair genes including Ogg1 were reported in human liver, ovary, kidney, breast, and colon cancers." (PMID 28785378, 2017). "In DMBDD-treated Ogg1−/− male mice, significantly enhanced incidence and multiplicity of colon tumors as compared to the Ogg1−/− control has been found." (PMID 28820464, 2017). "In previous studies, increase of repair-resistant oxidatively induced clustered DNA lesions in the human oxoguanine glycosylase 1 (Ogg1) gene and other repair enzymes were observed in patients with liver, ovary, kidney, breast, and colon cancers." (PMID 28785378, 2017). "Our previous studies also indicated higher frequency of OGG1 326 Cys/Cys genotype among lung and colon cancer patients, and 8-oxoGua excision activity was lower in patients with only Cys variant in comparison to those with Ser/Cys or only Ser variants." (PMID 25526641, 2014). "The adjusted ORs for the OGG1 Ser/Cys and Cys/Cys genotypes compared with the Ser/Ser genotype were not statistically significant (OR 1.28, 95%CI 0.55–2.99, p = 0.567 for colon cancer; OR 1.66, 95%CI 0.56–4.87, p = 0.359 for rectal cancer)." (PMID 18823566, 2008). "However, in females, inductions of colon tumors induced by DMBDD in Ogg1−/− and Ogg1+/+ animals were comparable, pointing out the sex differences in susceptibility to colonic tumorigenesis." (PMID 28820464, 2017). "This suggests reciprocal influence of PARP-1 and OGG1 on their expression and stability, and may contribute to progression of colon cancer." (PMID 25526641, 2014). "Moreover, in male, but not female DMBDD-treated Ogg1−/− mice, incidences of colon tumors and fibrosarcomas, were elevated." (PMID 28820464, 2017).
skin cancer (6 papers, 2012 to 2023). "The present study shows higher expression of OGG1 in skin cancer tissue due to chronic exposure to iAs." (PMID 34837924, 2021). "Also, in vitro and in vivo experiments suggested a putative role in skin cancer prevention of OGG-1, another DNA repair enzyme derived from the mustard plant Arabidopsis thaliana, even its effective efficacy has yet to be confirmed in the clinical setting." (PMID 36160127, 2022).
Cognitive impairment (5 papers, 2016 to 2025). Abnormal cognition is characterized by deficits in thinking, reasoning, or remembering. "This is further supported by the strong association of gene expression changes with brain-related diseases and cognitive impairment upon loss of both Ogg1 and Mutyh." (PMID 40779073, 2025). "When knocking out Mth1 and Ogg1 genes in 3xTg-AD, a commonly used genetic AD mouse model, MTH1 and OGG1 deficiency leads to a significant increase in 8-oxoG accumulation in nuclear genomes, accelerating microglial activation, neuronal degeneration, and cognitive deficit at 4–5 months of age." (PMID 39063016, 2024). "Nonetheless, some studies have suggested that OGG1 deficiency may contribute to neurodegeneration, cognitive impairment and neuroinflammation." (PMID 38969725, 2024). "Here, we compared the expression of BER components APE1, OGG1, PARP1 and Polβ in blood and postmortem brain tissue from patients with AD, mild cognitive impairment (MCI) and healthy controls (HC)." (PMID 27234294, 2016).
depression (5 papers, 2012 to 2025). "Furthermore, a previous study demonstrated that single nucleotide polymorphisms (SNPs) in OGG1 and MUTYH are associated with depression, further emphasizing a significant role of DNA glycosylases in affect regulation and mental health." (PMID 40779073, 2025).
glaucoma (5 papers, 2017 to 2023). Increased pressure in the eyeball due to obstruction of the outflow of aqueous humor. "As further support for the impact of oxidative stress on DNA in glaucoma, a negative correlation between base excision repair gene expression (PARP1 and OGG1) and the 8-OHdG level has been detected in the plasma of glaucoma patients." (PMID 36837806, 2023). "The expression of poly (ADP-ribose) polymerase (PARP1) and 8-oxoguanine DNA glycosylase (hOGG1), the two key BER enzymes, is significantly decreased in glaucoma patient cells." (PMID 36835325, 2023).
Huntington disease (5 papers, 2011 to 2020). Huntington disease (HD) is a rare neurodegenerative disorder of the central nervous system characterized by unwanted choreatic movements, behavioral and psychiatric disturbances and dementia. "In addition, inhibition of OGG1 holds promise to prevent or delay the onset of Huntington’s disease in risk groups." (PMID 32354123, 2020). "In the Huntington’s disease mouse model, Ogg1 knockout suppresses the repeat number growth in the striatum and delays the onset of motor dysfunction." (PMID 32354123, 2020). "Inhibition of OGG1 to prevent somatic trinucleotide repeat expansion in Huntington’s disease also has high priority due to the extreme morbidity and mortality of the condition and the lack of other drugs, although lead compounds capable of brain delivery have not been reported so far." (PMID 32354123, 2020). "In Huntington disease (HD), Ogg1 (and/or Neil1)-initiated repair of 8-oxoguanine (8-oxoG, or oxidized pyrimidines) in CAG triplets is proposed to trigger iterative oxidation–excision cycles that contribute to the somatic instability of the huntingtin gene, through a CAG repeat expansion." (PMID 32192183, 2020).
leukemia (5 papers, 2006 to 2022). A malignant (clonal) hematologic disorder, involving hematopoietic stem cells and characterized by the presence of primitive or atypical myeloid or lymphoid cells in the bone marrow and the blood. "In leukemia patients, those with high OGG1 expression has a poor prognosis and a higher risk of relapse." (PMID 36528059, 2022). "A similar observation was made in KG-1 human leukemia cells with an OGG1 mutation." (PMID 29306194, 2018). "Next, in order to verify that Nrf2 regulates OGG1 through AKT signaling pathway to mediate drug resistance in leukemia cells, we verified the interaction between Nrf2 and OGG1 after inhibition of AKT signaling pathway by ChIP." (PMID 36528059, 2022). "The number of PB-treated surviving Ogg1−/− male and female mice started to decrease at weeks 52 and 55, respectively, mostly due to the development of malignant lymphomas/leukemias (females) and HCCs (males and females)." (PMID 28785378, 2017). "Spontaneous tumors, mostly malignant lymphomas/leukemias, developed in PB-administered Ogg1+/+ male mice were the reason of their earlier mortality." (PMID 28785378, 2017). "Neoplastic nodules induced in the DMBDD-treated group of Ogg1−/− and Ogg1+/+ mice were mainly lung, liver, colon, small intestine, urinary bladder tumors, malignant lymphomas/leukemias and subctaneous tumors (fibrosarcomas)." (PMID 28820464, 2017). "Malignant lymphomas/leukemias were found in PB-treated Ogg1−/− females (35%), and males (5%), and differences were significant in females (P < 0.05) as compared to control Ogg1−/− (0%) and PB-treated Ogg1+/+ (0%) mice." (PMID 28785378, 2017). "Trends for increase of malignant lymphomas/leukemias were observed in Ogg1 homozygous mutant males (15%) and females (20%) treated with DMBDD, as compared to wild type mice." (PMID 28820464, 2017). "In vitro, Nrf2 and OGG1 were highly expressed in drug-resistant leukemia cells." (PMID 36528059, 2022). "In vivo, downregulation of Nrf2 could increase the sensitivity of leukemia cell to cytarabine and decrease OGG1 expression." (PMID 36528059, 2022). "Furthermore, trends for increase of incidences of malignant lymphomas/leukemias induced by the DMBDD treatment in Ogg1−/− mice as compared to the Ogg1−/− controls and DMBDD-treated Ogg1+/+ animals were found." (PMID 28820464, 2017). "Furthermore, the use of OGG1 inhibitor TH5487 could partially reverse the inhibitory effect of upregulated Nrf2 on leukemia cell apoptosis." (PMID 36528059, 2022). "Meanwhile, we found that Nrf2 could positively regulate OGG1 expression in leukemia cells." (PMID 36528059, 2022). "However, it remains unclear whether there exists a binding between Nrf2 and OGG1 in leukemia cells." (PMID 36528059, 2022). "Furthermore, downregulation of OGG1 could increase the sensitivity of leukemia cells to Ara-C." (PMID 36528059, 2022). "Therefore, this study further explored the effects of Nrf2, OGG1, and AKT signaling on leukemia cells." (PMID 36528059, 2022). "There existed no obvious difference in Nrf2 expression in leukemia cells treated with MK-2206, but the protein levels of p-AKT and OGG1 decreased significantly, whereas Cleaved-caspase 9 increased significantly." (PMID 36528059, 2022).
squamous cell carcinoma (5 papers, 2002 to 2012). A carcinoma arising from squamous epithelial cells. "The crude and adjusted ORs for the OGG1 Ser/Cys or Cys/Cys genotypes compared with the Ser/Ser genotype were not significant for adenocarcinoma and squamous cell carcinoma." (PMID 19161591, 2009).
acute myeloid leukemia (4 papers, 2022 to 2025). Acute myeloid leukemia (AML) is a group of neoplasms arising from precursor cells committed to the myeloid cell-line differentiation. "However, OGG1 has also been implicated in the molecular underpinning of acute myeloid leukemia." (PMID 38201575, 2023). "An earlier study also indicated that higher OGG1 expression negatively impacts disease outcomes such as relapse-free survival in patients with acute myeloid leukemia (AML)." (PMID 39741341, 2025). "In acute myeloid leukemia (AML), OGG1 S326C was observed more frequently in patients experiencing relapse compared to other patients (28.9% vs. 8.9%, odds ratio = 4.10, 95% confidence interval = 1.35–12.70, p = 0.01), and those with the S326C variant exhibited a shorter relapse-free survival." (PMID 38201575, 2023).
autism (4 papers, 2012 to 2017). Persistent deficits in social interaction and communication and interaction as well as a markedly restricted repertoire of activity and interest as well as repetitive patterns of behavior. "Loss or decrease in OGG1 levels and increase of 8-oxodG in the genome have been reported in cancer, neurodegenerative diseases, autism, and metabolic diseases, as well as in brain aging." (PMID 28758896, 2017). "Similar alterations in 8-oxodG in cerebellar tissue from humans with autism and BTBR T+tf/J mouse model warrant future large-scale studies to specifically address the role genetic alterations OGG1 in pathogenesis of autism in human population." (PMID 25423485, 2014). "A lack of Ogg1 in the brain resulted in multiple cellular and molecular events, including increased apoptosis and aberrant neuronal connectivity, key pathomorphological features of autism." (PMID 25423485, 2014).